HOXC8 (homeobox C8)
Diseases named in the same sentence as HOXC8 in open-access papers (continued):
Sharing a sentence is not in itself a finding about the gene and the disease.
cancer (continued). "We found that HOXC8 shRNA knockdown in A549 or NCI-H460 cells significantly inhibited the colony formation of the cancer cells, and ectopic expression of HOXC8 enhanced the colony formation of cancer cells." (PMID 29367650, 2018). "Hence, the present findings provide additional insights regarding the implication of HOXC8 and target genes in EMT as well as malignant tumor progression." (PMID 32922885, 2018). "Importantly, the expression differences between the cancer specimens and normal tissues were all statistically significant for CDH11 (P < 0.0001), ILF3 (P = 0.017) or HOXC8 (P = 0.004)." (PMID 29296180, 2017). "As the CD44+/CD24− population can identify both CSC and early progenitor cells, we also stained HOXC8-expressing cancer cells with the PKH26 dye and studied the ability of HOXC8 to regulated the more primitive and quiescent CSC population which is able to retain the dye upon cell proliferation." (PMID 28202042, 2017). "The results showed that some HOX genes in pan-cancer had significant strong correlation (R≥0.8): HOXA9 with HOXA10, HOXB5 with HOXB6 and HOXB8, HOXB8 with HOXB6 and HOXB9, HOXB3 with HOXB4 and HOXB5 and HOXB6, HOXC8 with HOXC9, HOXC9 with HOXC10, HOXD10 with HOXD11." (PMID 39980564, 2025). "In general, the role of HOXC8 in cancer development has not yet been clearly defined." (PMID 21712827, 2011).
adenocarcinoma (1 paper, 2018). A common cancer characterized by the presence of malignant glandular cells. "We found that HOXC8 showed high alteration frequency in NSCLC, particularly in adenocarcinoma, in comparison with small lung cancer." (PMID 29367650, 2018).
HOXC8 also shares sentences with these, for which no sentence is quoted: Obesity (3 papers); acute lymphoblastic leukaemia (2); glioblastoma (2); prostate tumors (2); triple-negative breast carcinoma (2); Alzheimer disease (1); arthrogryposis multiplex congenita (1); cholangiocarcinoma (1); endometrial cancer (1); esophageal cancer (1); gastrointestinal tumors (1); hip fracture (1); keloid (1); leukemia (1); lung squamous cell carcinoma (1); malignant lymphoma (1); nasopharyngeal carcinoma (1); neuroblastoma (1); neurofibroma (1); oesophageal adenocarcinoma (1); pancreatic adenocarcinoma (1); pancreatic neuroendocrine neoplasm (1); Parkinson disease (1); periodontitis (1); primary immunodeficiency (1); renal carcinoma (1); Wilms tumor (1).